EPM2A (EPM2A glucan phosphatase, laforin)
Description:
Plays an important role in preventing glycogen hyperphosphorylation and the formation of insoluble aggregates, via its activity as glycogen phosphatase, and by promoting the ubiquitination of proteins involved in glycogen metabolism via its interaction with the E3 ubiquitin ligase NHLRC1/malin. Shows strong phosphatase activity towards complex carbohydrates in vitro, avoiding glycogen hyperphosphorylation which is associated with reduced branching and formation of insoluble aggregates. Dephosphorylates phosphotyrosine and synthetic substrates, such as para-nitrophenylphosphate (pNPP), and has low activity with phosphoserine and phosphothreonine substrates (in vitro). Has been shown to dephosphorylate MAPT (By similarity). Forms a complex with NHLRC1/malin and HSP70, which suppresses the cellular toxicity of misfolded proteins by promoting their degradation through the ubiquitin-proteasome system (UPS). Acts as a scaffold protein to facilitate PPP1R3C/PTG ubiquitination by NHLRC1/malin. Also promotes proteasome-independent protein degradation through the macroautophagy pathway. [Isoform 2]: Does not bind to glycogen. Lacks phosphatase activity and might function as a dominant-negative regulator for the phosphatase activity of isoform 1 and isoform 7. [Isoform 7]: Has phosphatase activity (in vitro).
Synonyms: LDE; LD; EPM2; MELF; MELF2
Tractability: Antibody: UniProt places it where antibodies can reach, with high confidence; its Gene Ontology location is reachable by antibodies, with medium confidence. PROTAC: UniProt records ubiquitination sites on it; ubiquitination databases record sites on it.
Gene: Protein-coding gene on chromosome 6 (145,382,535 to 145,736,023, reverse strand). Ensembl gene ENSG00000112425.
Subcellular location: Cytoplasm; Cytoplasm (Isoform 1); Endoplasmic reticulum membrane; Cell membrane; Cytoplasm (Isoform 2); Nucleus; Cytoplasm (Isoform 4); Cytoplasm (Isoform 5); Cytoplasm (Isoform 7)
Subcellular location (Human Protein Atlas): Nucleoplasm
Pathways (Reactome):
Disease: Myoclonic epilepsy of Lafora
Metabolism: Glycogen synthesis
Genetic constraint (gnomAD): Loss-of-function variants: 22 observed, 26.38 expected, observed/expected ratio (o/e) 0.83, 90% interval 0.6 to 1.19. The synonymous counts are far from expectation, so gnomAD's model fits this gene poorly and the ratio says little. Missense variants: 450 observed, 397.57 expected, observed/expected ratio (o/e) 1.13, 90% interval 1.05 to 1.22. Synonymous variants: 217 observed, 159.5 expected, observed/expected ratio (o/e) 1.36, 90% interval 1.22 to 1.52.
Gene-disease validity (ClinGen):
ClinGen rates the evidence that EPM2A causes each of these diseases.
Lafora disease (autosomal recessive): Definitive. Lafora disease (LD) is a rare, inherited, severe, progressive myoclonic epilepsy characterized by myoclonus and/or generalized seizures, visual hallucinations (partial occipital seizures), and progressive neurological decline.
Homologues: Orthologues: chimpanzee EPM2A (99% identical), macaque EPM2A (98% identical), dog EPM2A (95% identical), pig EPM2A (92% identical), rat Epm2a (91% identical), mouse Epm2a (89% identical), tropical clawed frog epm2a (66% identical), zebrafish epm2a (61% identical), guinea pig EPM2A (54% identical). Paralogues in human: SSH1 (20% identical), SSH2 (20% identical), DUSP2 (19% identical), SSH3 (19% identical), DUSP9 (18% identical), DUSP5 (17% identical), DUSP7 (17% identical), DUSP1 (17% identical), DUSP16 (16% identical), DUSP10 (15% identical), DUSP4 (15% identical), DUSP6 (15% identical), and 19 more.
Diseases named in the same sentence as EPM2A in open-access papers:
EPM2A is named in the same sentence as 44 diseases in open-access papers, as found by Europe PMC text mining. Sharing a sentence is not in itself a finding about the gene and the disease. The quoted sentences say what the papers report.
Lafora disease (42 papers, 2009 to 2026). "Mutations in the EPM2A gene, a glucan phosphatase, are linked to Lafora disease and disrupt autophagy initiation." (PMID 41277110, 2026). "Lafora disease is a fatal neurodegenerative disorder caused by loss-of-function mutations in the EPM2A or EPM2B genes, which encode laforin and malin, respectively." (PMID 41465357, 2025). "Next-generation sequencing (NGS) identified a pathogenic mutation in the EPM2A gene (encoding laforin) on chromosome 6, confirming a diagnosis of Lafora Disease (LD)." (PMID 41018191, 2025). "For example, FANCL has been associated with Fanconi anemia and premature ovarian insufficiency, and EPM2A has been linked to Lafora disease." (PMID 38886689, 2024). "Lafora disease (LD), a fatal neurodegenerative disorder, is caused by mutations in the EPM2A gene encoding laforin phosphatase or NHLRC1 gene encoding malin ubiquitin ligase." (PMID 39301689, 2024). "One likely pathogenic EPM2A variant associated with Lafora disease, and one likely pathogenic SCN1A variant associated with DS were identified on the epilepsy panel." (PMID 38756210, 2024). "Lafora disease is a rare disorder caused by loss of function mutations in either the EPM2A or NHLRC1 gene." (PMID 36899857, 2023). "Lafora disease is caused by loss-of-function mutations in the EPM2A gene, coding for a protein phosphatase (laforin), or of the NHLRC1 gene, coding for an E3 ubiquitin ligase (malin)." (PMID 38033781, 2023). "Lafora Disease (LD), first described in 1911, is a rare progressive myoclonus epilepsy due to biallelic pathogenic variants in EPM2A or EPM2B." (PMID 37107612, 2023). "Patients with Lafora disease have a mutation in EPM2A or EPM2B, resulting in dysregulation of glycogen metabolism throughout the body and aberrant glycogen molecules that aggregate into Lafora bodies." (PMID 37700152, 2023). "Lafora disease (LD) is a progressive neurologic disorder caused by biallelic pathogenic variants in EPM2A or EPM2B, leading to tissue accumulation of polyglucosan aggregates termed Lafora bodies (LBs)." (PMID 37107612, 2023). "Lafora disease-causing mutations in the EPM2A gene represent approximately 60% and in the EPM2B gene 35% of patients with Lafora disease." (PMID 34069559, 2021). "Mutations in the genes encoding for malin (EPM2B) or laforin (EPM2A) result in Lafora disease, a form of progressive myoclonus epilepsy." (PMID 33802079, 2021). "Loss-of-function mutations in either EPM2A or EPM2B (the gene that encodes malin) are most notably associated with Lafora disease, a very rare autosomal recessive progressive myoclonus epilepsy." (PMID 34329319, 2021). "Another study has identified patients with Lafora disease as showing progressive myoclonic epilepsy and the mutation of glucan phosphatases EPM2A and EPM2B." (PMID 31185666, 2019). "Lafora progressive myoclonus epilepsy (Lafora disease) is a rare, usually childhood-onset, fatal neurodegenerative disease caused by biallelic mutations in EPM2A (Laforin) or EPM2B (NHLRC1; Malin)." (PMID 32587944, 2019). "Lafora disease (LD) is an autosomal recessively inherited disease that results from mutations in either the gene encoding for laforin (EPM2A) or malin (EPM2B, also called NHLRC1)." (PMID 28800070, 2017). "Recessive mutations/microdeletions of EPM2A cause progressive myoclonic epilepsy type 2A (Lafora disease, OMIM #254780)." (PMID 25950944, 2015). "Mice with mutated EPM2A gene develop many of the characteristics of Lafora disease, since they show LBs in liver, muscle and brain, as well as impaired behavioural responses, ataxia and ultimate appearance of spontaneous myoclonic seizures." (PMID 24472629, 2014). "Lafora disease is an autosomal recessive form of progressive myoclonic epilepsy caused by defects in the EPM2A and EPM2B genes." (PMID 24472629, 2014).
Lafora disease (continued). "Lafora disease can be caused by defects in the EPM2A gene, which encodes the laforin protein phosphatase, or in the NHLRC1 gene (also called EPM2B) codifying the malin E3 ubiquitin ligase." (PMID 24472629, 2014). "Mutations in EPM2A result in a rare, progressive myoclonus epilepsy called Lafora disease (LD, OMIM 254780)." (PMID 23922729, 2013). "Lafora disease (LD) is caused by recessively inherited mutations in the EPM2A or EPM2B genes, encoding laforin (a carbohydrate binding phosphatase) and malin (an E3 ubiquitin ligase)." (PMID 21552327, 2011). "Autosomal recessive mutations in EPM2A cause Lafora disease (LD)." (PMID 21887368, 2011). "We aimed to identify modifier genes that may contribute to the clinical course of Lafora disease patients with EPM2A or EPM2B mutations." (PMID 21738631, 2011). "EPM2A (epilepsy of progressive myoclonus type 2) is mutated in ~50% LD cases." (PMID 19545434, 2009). "Similarly, abnormal p-tau in the form of NFTs are also observed in the Epm2a–/– mouse model, which replicates many of the features of Lafora disease caused by EPM2A mutations, including laforin deficiency, neuronal degeneration, spontaneous epileptic activity, and the development of Lafora bodies." (PMID 35923547, 2022). "Expression levels of miRNAs linked to NHLRC1 and EPM2A genes (miR‐326 for NHLRC1 and miR‐383‐5p for EPM2A), key to Lafora Disease (LD) pathogenesis, were evaluated." (PMID 40542608, 2025). "We previously demonstrated the efficacy of gene therapy using intracerebroventricular delivery of rAAV2/9 vectors expressing EPM2A or EPM2B in mouse models of Lafora disease." (PMID 41169091, 2025). "It has been shown that Epm2a knockout (KO) and Epm2b KO mouse models replicate essential features of Lafora disease, such as neuronal degeneration and accumulation of Lafora bodies in muscle, liver, and brain." (PMID 35847198, 2022). "Loss-of-function pathogenic variants in EPM2A or EPM2B lead to an accumulation of Lafora bodies (an abnormal form of glycogen that cannot be metabolized) and subsequent Lafora disease." (PMID 35847198, 2022). "Several experimental models of Lafora disease have been generated by deleting the Epm2a or Epm2b genes in mice." (PMID 34069559, 2021). "Epm2a−/− and Epm2b−/− mouse models of Lafora disease present alterations in the volume of the hippocampus and cerebellum." (PMID 33092303, 2020). "Mutations in the EPM2A and EPM2B genes, encoding laforin and malin proteins respectively, are responsible for Lafora disease, a fatal form of progressive myoclonus epilepsy with autosomal recessive inheritance." (PMID 33092303, 2020). "In this article, we explore for the first time the alterations observed in brain volume, glucose metabolism and brain metabolites through in vivo MRI, FDG-PET and 1H-MRS ex vivo studies, in both Epm2a−/− and Epm2b−/− mouse models of Lafora disease." (PMID 33092303, 2020). "Epm2b−/− mice show brain metabolic changes comparable to those present in Epm2a−/− mice and in some brain regions of patients with Lafora disease, although Epm2b−/− mice shows milder volumetric alterations and normal glucose metabolism." (PMID 33092303, 2020). "Null mouse models of Lafora disease have been generated by gene targeting deletion of either Epm2a or Epm2b genes." (PMID 33092303, 2020). "Lafora disease (LD, OMIM 254780) is a fatal neurodegenerative disorder produced mainly by mutations in two genes: EPM2A, encoding the dual specificity phosphatase laforin, and EPM2B, encoding the E3-ubiquitin ligase malin." (PMID 26493215, 2015). "Several transgenic mouse models have been developed for Lafora disease, either by disruptiing EPM2A gene (null mice) or by over-expressing inactivated laforin in all tissues." (PMID 24472629, 2014). "Two genes are now known to be involved in Lafora disease: EPM2A and EPM2B." (PMID 35847198, 2022).
Lafora disease (continued). "Lafora disease (LD, OMIM# 254780) is an autosomal recessive neurodegenerative disorder caused by loss-of-function mutations in either the laforin glycogen phosphatase gene (EPM2A) or the malin ubiquitin E3 ligase (NHLRC1)." (PMID 36277909, 2022). "Therefore we suggest that the imbalance between neuron populations in EPM2A-/- mice disturb the cortical network resulting in the pathogenesis of Lafora disease." (PMID 24472629, 2014). "Thus, the aim of our study is to elucidate the molecular mechanism of the pathology by characterizing cerebral cortex neurodegeneration in the well accepted murine model of Lafora disease EPM2A-/- mouse." (PMID 24472629, 2014). "Lafora disease patients present a distinctive EEG pattern characterized by slowing of background activity with recurrent epileptiform discharges: 3–6 Hz spikes/polyspikes, with or without slow waves, similar to that observed in spontaneous seizures developed by Epm2a−/− and Epm2b−/− mice." (PMID 25309313, 2014).
epilepsy (13 papers, 2014 to 2025). A brain disorder characterized by episodes of abnormally increased neuronal discharge resulting in transient episodes of sensory or motor neurological dysfunction, or psychic dysfunction. "Among the epilepsy panel findings in our cohort, we were only able to find functional studies for the two known disease-associated variants in the genes EPM2A and SCN1A." (PMID 38756210, 2024). "Patients who are screened for epilepsy genes and identify mutations in EPM2A or EPM2B could potentially receive this treatment to prevent glycogen accumulation and LD aggregation in the brain." (PMID 37700152, 2023). "The downregulation of this channel has generally been described in inflammatory states, but impaired function of Kir4.1 has also been associated with autism–epilepsy phenotypes in humans, and we therefore cannot exclude a possible role for it in the epileptic phenotype observed in epm2a KO larvae." (PMID 36551859, 2022). "There is no obvious relationship between the identified hub genes and the lipid metabolism, e.g., EIF3J (eukaryotic translation initiation factor 3 subunit J), EPM2A (epilepsy, progressive myoclonus type 2A), and CALM1 (calmodulin 1)." (PMID 33117416, 2020). "“Epilepsy” is used for search, 43 genes (such as the gene, EPM2A, presented a relevance score of 88.82) compiled from “Gene cards” and “Disease” database are related to epilepsy." (PMID 28380454, 2017). "Microdeletions found only in GGE patients harboured a high proportion of genes previously associated with epilepsy and neuropsychiatric disorders (NRXN1, RBFOX1, PCDH7, KCNA2, EPM2A, RORB, PLCB1)." (PMID 25950944, 2015). "This hippocampal‐striatal cross‐talk is affected in several neurological disorders, including epilepsy, potentially leading to an imbalance between two memory systems, an imbalance that may also be present in Epm2a−/− mice." (PMID 41169091, 2025). "Conversely, an increase in the expression levels of SLIT and NTRK-like family, member 1 (Slitrk1), TYRO3 protein tyrosine kinase 3 (Tyro3), epilepsy, progressive myoclonic epilepsy, type 2 gene alpha (Epm2a), fucosyl-transferase 9 (Fut9), immunoglobulin superfamily, member 9B (Igsf9b) was observed." (PMID 38535448, 2024). "These microdeletions affected 158 protein-coding RefSeq genes and exhibited an enrichment of genes previously associated with epilepsy (NRXN1, RBFOX1, PCDH7, KCNA2, EPM2A, RORB, PLCB1) and neuropsychiatric disorders (DPYD, CADM2, PARK2, GRM8, TSNARE1, TPH2, MACROD2)." (PMID 25950944, 2015). "In the present era, patients with LD are diagnosed comparatively swiftly because EPM2A and NHLRC1 are included in most epilepsy gene panels, and therefore, most new patients would benefit." (PMID 33277363, 2021).
progressive myoclonus epilepsy (10 papers, 2014 to 2023). A rare group of disorders characterized by the development of myoclonic and tonic-clonic epileptic seizures associated with progressive degeneration of the nervous system. "LD is a fatal progressive myoclonus epilepsy caused by loss of function mutations in the EPM2A or EPM2B gene." (PMID 35347645, 2022). "Lafora disease (LD; EPM2A/B; OMIM #254780) is a severe form of progressive myoclonus epilepsy inherited in an autosomal recessive mode and caused by biallelic mutations in EPM2A (Laforin) or EPM2B (NHLRC1; Malin)." (PMID 32587944, 2019). "Variants in EPM2A or EPM2B were detected by NGS in all 11 index patients with suspected LD or unclassified progressive myoclonus epilepsy." (PMID 32587944, 2019). "Lafora disease is a rare form of inherited progressive myoclonus epilepsy caused by mutations in the EPM2A gene encoding laforin, or in the EPM2B gene, which encodes malin." (PMID 25309313, 2014). "Lafora Disease (LD, OMIM# 254780) is an autosomal recessive progressive myoclonic epilepsy (PME) caused by loss-of-function mutations in either the EPM2A (OMIM # 607566) gene, encoding the laforin glycogen phosphatase, or the NHLRC1 (OMIM # 608072) gene, encoding the malin ubiquitin E3 ligase." (PMID 37448753, 2023). "Homozygous deletions in the EPM2A gene result in progressive myoclonus epilepsy (PME) with Lafora bodies (OMIM 254780)." (PMID 24497844, 2014).
Ataxia (2 papers, 2014 to 2019). Ataxia refers to impaired coordination of voluntary muscle movement. "The patients bearing novel variants in EPM2A or EPM2B had typical disease onset during adolescence and developed characteristic symptoms including multiple types of seizures, ataxia, dysarthria and dysphagia, as well as cognitive decline during the disease course." (PMID 32587944, 2019).
Dyskinesia (2 papers, 2020 to 2025). A movement disorder which consists of effects including diminished voluntary movements and the presence of involuntary movements. "Mouse models lacking laforin (Epm2a−/−) or malin (Epm2b−/−) expression exhibit neurological alterations that closely resemble those observed in patients with LD, including the presence of LBs, dyskinesia, impaired motor activity and coordination, deficits in episodic memory, and epileptic activity." (PMID 41465357, 2025).
bladder cancer (1 paper, 2022). "Decreased expression levels of EPM2A were observed in most tumors, such as PCA and bladder cancer, compared to normal tissues (p < 0.05, 21/22)." (PMID 36199693, 2022).
Cerebellar atrophy (1 paper, 2020). Cerebellar atrophy is defined as a cerebellum with initially normal structures, in a posterior fossa with normal size, which displays enlarged fissures (interfolial spaces) in comparison to the foliae secondary to loss of tissue. "MRI studies in patients showed the presence of diffuse cerebral, cortical and/or cerebellar atrophy, findings opposite to those observed in equivalent brain regions of Epm2a−/− mice." (PMID 33092303, 2020).
Cerebral atrophy (1 paper, 2022). Atrophy (wasting, decrease in size of cells or tissue) affecting the cerebrum. "De novo mutations in NACC1 and disruption in EPM2A gene can lead to cerebral atrophy and infantile epilepsy." (PMID 36077118, 2022).
Dystonia (1 paper, 2025). An abnormally increased muscular tone that causes fixed abnormal postures. "Intragenic deletions and duplications can be found in the EPM2A and NHLRC1 (EPM2) genes, ASAH1 gene (SMA-PME), NUS1, and SGCE (myoclonus-dystonia)." (PMID 40584247, 2025).
glycogen storage diseases (1 paper, 2022). "A subsequent study performed in Epm2a−/− and Epm2b−/− mice confirmed that PBs colocalize in neurons, astrocytes, and microglial cells and that the formation of astrocytic PBs precedes that of neuronal PBs, as is the case of other glycogen storage diseases." (PMID 36551859, 2022).
memory impairment (1 paper, 2025). "Epm2a−/− and Epm2b−/− mice exhibit motor and memory impairments, epileptic activity, and molecular and histological abnormalities." (PMID 41465357, 2025).
myoclonus epilepsy (1 paper, 2023). "Lafora disease is a progressive fatal autosomal recessive form of myoclonus epilepsy, caused by loss-of-function mutations of EPM2A or NHLRC1 genes, encoding the glycogen phosphatase laforin and the E3 ubiquitin ligase malin, respectively." (PMID 36935052, 2023).
prostate carcinoma (1 paper, 2022). A carcinoma that arises from epithelial cells of the prostate gland. "EPM2A encodes a dual specificity phosphatase and has been proven to be a potential biomarker in several cancers but has not been mentioned in prostate cancer (PCA)." (PMID 36199693, 2022).